MPO (myeloperoxidase)
Diseases named in the same sentence as MPO in open-access papers (continued):
Sharing a sentence is not in itself a finding about the gene and the disease.
bronchiectasis (16 papers, 2015 to 2026). Segmental, irreversible dilation of the bronchial tree resulting in the accumulation of secretions which leads to obstruction. "These MPO-ANCA patientswith bronchiectasis have an increased risk of peripheral nerve involvement and areduced frequency of renal involvement." (PMID 36743820, 2023). "Evolving literature suggests that MPO-ANCA+ patients are at higher risk for bronchiectasis, which is often present prior to AAV presentation." (PMID 31867013, 2019). "The high proportion of MPO-ANCA+ patients with bronchiectasis raises the question of whether it might predispose to MPO-ANCA+ AAV, be more likely to complicate MPO-ANCA+ AAV, or go undetected for some time before AAV comes to medical attention." (PMID 31867013, 2019). "This study suggests the MPO-DNA complex as a potential biomarker and pathogenic factor associated with disease severity, and proposes a dual-target combined intervention strategy worthy of further preclinical investigation for P. aeruginosa-associated bronchiectasis." (PMID 41571945, 2026). "Neutrophil-derived proteins, including NE, MPO, and MMPs, were also increased in patients with bronchiectasis." (PMID 36902466, 2023). "Central airways disease, withcavitatory lesions and/or nodules are more prevalent in PR3-ANCA+patients, whereas, MPO-ANCA+ patients are more likely to have usualinterstitial pneumonia (UIP) pattern ILD or bronchiectasis." (PMID 36743820, 2023). "A previous analysis of 385 patients with bronchiectasis showed that bacterial density was directly correlated with airway and systemic inflammatory markers, such as myeloperoxidase activity, neutrophil elastase activity, and tumor necrosis factor-α levels." (PMID 33573691, 2021). "The presence of MPO in the bronchoalveolar lavage fluid of patients with CF has been found to strongly correlate with development of bronchiectasis, as does methionine sulfoxide, a by-product of MPO activity." (PMID 32397175, 2020). "In the other, MPO-ANCA+ subjects were twice as likely to have bronchiectasis (31% vs. 15%) and the bronchiectasis was more severe among the MPO-ANCA+ subjects." (PMID 31867013, 2019). "In two recent cohort studies, MPO-ANCA+ subjects were found to have bronchiectasis more often than PR3-ANCA+ subjects." (PMID 31867013, 2019). "Greater MPO concentrations have previously been correlated with increased mucus plugging in bronchiectasis, suggesting that MPO could impair mucociliary transport." (PMID 42063333, 2026). "Additionally, LXA4 reduced neutrophil degranulation and release of myeloperoxidase in a concentration-dependent manner from neutrophils isolated from healthy volunteers and in patients with mild and moderate–severe bronchiectasis." (PMID 34789559, 2021). "• Why might fibrotic lung disease and bronchiectasis be more common in MPO-ANCA+ AAV? • Why is renal disease more severe at presentation in MPO-ANCA+ AAV? • Why does PR3-ANCA+ AAV tend to affect the upper airway more often?" (PMID 31867013, 2019). "The most comprehensive BALF study in adult non-CF bronchiectasis demonstrated increased levels of neutrophil elastase, myeloperoxidase, TNF-α, IL-6 and IL-8 but not IL1β compared to controls." (PMID 25822228, 2015).
gingivitis (16 papers, 2015 to 2025). A disorder involving inflammation of the gums; may affect surrounding and supporting structures of the teeth. "Then, as gingivitis progresses to PD, H3Cit plasma levels decrease because histones are degraded by MPO and other PMN enzymes." (PMID 39339210, 2024). "Previously, higher salivary MPO concentrations were reported in patients with chronic PD compared with healthy controls and gingivitis patients." (PMID 39339210, 2024). "Significantly higher serum myeloperoxidase levels were observed in PCOS patients with gingivitis than generally healthy individuals with gingivitis." (PMID 37569455, 2023). "This study demonstrated that the MMP-8 and MPO levels are suitable for diagnosing gingivitis based on significant results obtained in both correlation and ROC curve analyses." (PMID 32503210, 2020). "MPO, being related to neutrophils, may be present more in gingivitis than in chronic disease, where other defense cells are also related." (PMID 40710166, 2025). "MMP-8 and MPO displayed the greatest sensitivity towards gingivitis." (PMID 35453967, 2022). "In summary, MMP-8 and MPO have now been shown to be effective in diagnosing gingivitis." (PMID 32503210, 2020). "MMP-8 and MPO were found to be effective for diagnosing gingivitis." (PMID 32503210, 2020). "MPO also showed a large AUC and a strong correlation with gingivitis in the present study." (PMID 32503210, 2020). "MPO and MMP-8 levels in saliva were strongly correlated with gingivitis, with Pearson’s correlation coefficients of 0.399 and 0.217, respectively." (PMID 32503210, 2020). "This study aimed to evaluate the effects of tobacco smoking on GCF levels of neutrophil enzymes (myeloperoxidase (MPO), beta-glucuronidase (BGD), neutrophil elastase (NE) and periodontal parameters in healthy young adults with dental plaque biofilm-induced gingivitis." (PMID 34360367, 2021). "Previous studies have shown increased MPO levels in the GCF of patients with PCOS compared with healthy young women, while women with both PCOS and gingivitis were reported to exhibit significantly higher serum levels of MPO and MMP-9 than otherwise systematically healthy women with gingivitis." (PMID 32456146, 2020). "Difference in salivary MPO activity between gingivitis patients and control healthy subjects was observed but not significant (p = 0.181)." (PMID 27274868, 2016). "The present assay did not demonstrate significant differences in salivary MPO activity between gingivitis patients and periodontally healthy individuals (p = 0.181) but MPO activity in gingivitis patients tended to be higher than in periodontally healthy individuals." (PMID 27274868, 2016). "Although it is known that smoking has effects on neutrophils enzymatic activity, the effect of smoking on GCF levels of MPO, BGD, and NE in patients with gingivitis was not thoroughly investigated." (PMID 34360367, 2021). "After compensation for gingivitis, gingival pockets and smoking, the mean salivary levels of MMP-8 (543 vs 440 ng/mL, p = 0.003) and MPO (1899 vs 1637 ng/mL, p = 0.02) were higher in non-MI subjects compared to MI patients." (PMID 26132583, 2015).
pancreatic cancer (16 papers, 2015 to 2025). "In a mouse model of pancreatic cancer, MPO deficiency and pharmacological inhibition of MPO, when combined with immune checkpoint therapy, significantly delayed tumor growth." (PMID 40547041, 2025). "We compared treatment outcome, immune composition and characterized myeloid cells using wild-type, myeloperoxidase-deficient, and myeloperoxidase inhibitor treated wild-type mice using established subcutaneous pancreatic cancer models." (PMID 38367056, 2024). "Previous studies have also highlighted the significant role of MPO in other tumors, such as its involvement in the immune-suppressive microenvironment of pancreatic cancer and its potential biomarker value in ovarian cancer." (PMID 40547041, 2025). "Indole-3-acetic acid potentiates pancreatic cancer chemotherapy in mice via neutrophil-dependent myeloperoxidase oxidation, generating antiproliferative metabolites." (PMID 40906132, 2025). "Here, we evaluated the contribution of myeloperoxidase, a myeloid-lineage restricted enzyme and primary source of reactive oxygen species, to regulate immune checkpoint therapy response in preclinical pancreatic cancer models." (PMID 38367056, 2024). "This study used MUC1 as a marker for pancreatic tumor cells, MPO as a marker for neutrophils, and F4/80 to indicate murine macrophages." (PMID 37963142, 2023). "Similar to the previous reports, decrease of myeloperoxidase+ (MPO+) neutrophil infiltration was observed in the pancreatic tumor area in PKF2h mice." (PMID 30659170, 2019). "Unsurprisingly, we found high numbers of MPO‐positive cells in the stroma of pancreatic cancer, which are indicative of the infiltration of neutrophils or their precursors." (PMID 28783244, 2017). "Additionally, our data demonstrate an increase in MPO expression in pancreatic cancer compared to normal pancreas tissues." (PMID 38367056, 2024). "Repurposing myeloperoxidase specific inhibitors may provide a promising therapeutic strategy to expand therapeutic options for pancreatic cancer patients to include immunotherapies." (PMID 38367056, 2024). "Our previous study showed that the SETD2 expression level was closely related to H3K36me3 levels in pancreatic tumors.[8a] Here, we observed that the expression of SETD2/H3K36me3 was negatively correlated with MPO levels in pancreatic tumors (χ2 = 12.57, P < 0.001)." (PMID 36453584, 2023). "In pancreatic cancer, the indole analog of 3-ILA and 3-IA, indole-3-acetic acid (3-IAA), can be oxidized by myeloperoxidase to generate reactive oxygen species (ROS)." (PMID 41459217, 2025). "In fact, in gastrointestinal tumors treated with Th2 cells, we noted enhanced production of MPO and NOS2, which has cytotoxic effects on colon and pancreas cancer cells as we have previously noted." (PMID 36376448, 2023). "For example, it has been recently reported that TIMP-1 triggered neutrophil extracellular traps (NETs) formation in patients with pancreatic cancer and there was a significant correlation between TIMP-1 and DNA-bound myeloperoxidase, a NET marker in the plasma." (PMID 36482481, 2022). "To investigate the contribution of neutrophils to the systemic LCN-2 pool in pancreatic cancer patients with and without cachexia, we quantified circulating levels of reliable neutrophil activation markers calprotectin, MPO, elastase, and BPI in relation to levels of LCN-2." (PMID 37006254, 2023).
unstable angina (16 papers, 2007 to 2026). "In an attempt to identify AMI in patients presenting angina, Omran and colleagues (2018) have investigated the diagnostic efficiency of plasma MPO levels alone or in combination with creatine kinase (CK)-MB and Troponin I (cTnI) within the first 6 h of disease onset." (PMID 35740071, 2022). "Similar finding was seen in Calmarza and colleagues (2018), whereby the plasma MPO levels significantly increased in ACS patients compared to those with stable angina and yielded its best result at the 6th hour after hospital administration." (PMID 35740071, 2022). "Similar results regarding the effect of curcumin on MPO serum concentration in patients with unstable angina were found in the present study." (PMID 31516856, 2019). "By contrast, neutrophils from patients with unstable angina had a homogeneously reduced unimodal expression of MPO." (PMID 22761804, 2012). "Similar findings were replicated in a cohort of patients with NSTE-ACS or stable angina, where MPO levels were considerably higher in subjects with PE compared to the other entities (PE: 685.9 ng/mL vs. PR: 340.0 ng/mL vs. stable angina: 272.5 ng/mL, p < 0.001)." (PMID 38891972, 2024). "Similarly, a decrease of plasma lactoferrin and myeloperoxidase and increase of IL-6 were observed during 6–12 hours after stenting in unstable angina." (PMID 23967262, 2013). "Our composite endpoint did not include unstable angina, which may increase the association between MPO levels and cardiac outcomes." (PMID 23675127, 2009). "Another recently published study, which measured the levels of the enzymes in question, showed that plasma MPO concentrations show a significant inverse correlation with PON-1 levels in patients with stable and unstable angina." (PMID 36463116, 2022). "In accordance with these findings, we found that the prognostic value of MPO was the highest among studies with high proportion of AMI patients compared to those with higher percentage of unstable angina subjects." (PMID 31341419, 2019). "Results showed that administration of curcumin (80 mg/day) to patients with unstable angina was not able to reduce the level of MPO, IL-18 and MMP-9 biomarker." (PMID 31516856, 2019). "In the present study, nanocurcumin administration for 5 days to patients with unstable angina did not affect MPO, IL-18 and MMP-9 levels significantly." (PMID 31516856, 2019). "Results showed that administration of nanocurcumin (80 mg/day for five days) to patients with unstable angina could not reduce the level of MPO, IL-18 and MMP-9." (PMID 31516856, 2019).
abscesses (15 papers, 2005 to 2025). "MPO−/−-infected mice showed extensive neutrophilic infiltration with histiocytic and lobulated neutrophils, and multi-focal small abscesses." (PMID 38037141, 2023). "Liver lesions in WT and MPO−/− mice with hypoxic infection also showed extensive neutrophil infiltration and multi-focal small abscess formation." (PMID 38037141, 2023). "WT mice have MPO+ cells that surround and encompass the abscess, whereas Il1r1-/- mice show extensive MPO+ staining throughout the femur." (PMID 30978245, 2019). "Il1r1-/- mice with osteomyelitis have differential MPO staining in comparison to WT controls, suggesting these mice have disorganized abscess structure." (PMID 30978245, 2019). "To visualize immune cell infiltration and abscess structure, we conducted myeloperoxidase (MPO) staining on histologic sections of infected femurs at day 14 post-infection." (PMID 30978245, 2019). "MPO activity in abscesses provoked by 20 μg wt WTA after 48 h was significantly (P<0.0001) higher than that induced by 20 μg dltA WTA." (PMID 20949105, 2010). "MPO is present in the azurophilic granules of neutrophils and is routinely used to assess the tissue inflammatory responses and abscess formation." (PMID 20949105, 2010). "MPO staining of intestinal tissue revealed a marked increase in neutrophil accumulation in LF mice, with neutrophils predominantly clustered around crypt abscesses, indicating severe inflammatory infiltration of the intestinal mucosa." (PMID 41551600, 2025). "In contrast, infected skin samples from IL-1β−/− PMN→IL-1β−/− mice and IL-1β-deficient mice had markedly decreased neutrophil recruitment with minimal abscess formation and decreased myeloperoxidase (MPO) activity (which correlates with the degree of neutrophil infiltration)." (PMID 23209417, 2012). "This also aligns with the conventional definition of an abscess, and the combination of NMN and antibiotics significantly reduced MPO+ cell infiltration." (PMID 40742124, 2025). "Inflamed ears of MPO-/- mice exhibited the most affected phenotype, with severe damages of the epidermis, deep ulcers and PMN abscesses." (PMID 33391487, 2021). "This case is notable for its initial presentation mimicking cellulitis and abscess formation, diverting early suspicion from a hematologic origin.The diagnosis of MS requires histopathologic confirmation with immunohistochemical staining for markers such as CD34, CD43, and MPO." (PMID 41194805, 2025).
aneurysm (15 papers, 2018 to 2025). Bulging or ballooning in an area of an artery secondary to arterial wall weakening. "It is noteworthy that MPO-positive cerebral aneurysms have a higher risk of rupture than MPO-negative aneurysms within five years, as predicted by the PHASE model." (PMID 39654759, 2024). "Comparably, a study on cerebral aneurysms suggests that histological MPO presence positively correlates with 5-year aneurysm rupture risk." (PMID 34572424, 2021). "Investigations of resected aneurysms have found elevated levels of key proteins released from neutrophils, namely myeloperoxidase (MPO) and neutrophil gelatinase-associated lipocalin (NGAL) in the IA wall." (PMID 33059716, 2020). "There have been several recent studies that have directly implicated MPO activity in the pathogenesis of aneurysm formation, and, specifically, limited animal and human data for direct involvement of MPO in TAA." (PMID 33081376, 2020). "MPO is a serum inflammatory factor involved in tissue cell damage at the site of inflammation and is associated with the formation, development, and rupture of aneurysms." (PMID 38496021, 2024). "However, divergent results have been obtained for the correlation between myeloperoxidase content in IA wall and aneurysm rupture risk calculated with the PHASES score." (PMID 34743248, 2022). "Our histological stainings of AAA tissue confirmed that RNase A treatment was accompanied by reduced CD68+ macrophage infiltration, and neutrophil markers such as MPO tended to be decreased in gene expression analysis of RNase treated mouse aneurysms." (PMID 41173972, 2025). "Overall, we showed MPO inhibition can reduce arterial wall damage and prevent aneurysms progression in a preclinical model, consistent with other studies." (PMID 38509468, 2024). "Mn-TyrEDTA enhanced MRI showed promise as a noninvasive tool for monitoring aneurysm inflammation and the effects of MPO inhibition." (PMID 38509468, 2024). "Mn-TyrEDTA enhanced MRI revealed significantly higher MPO activity in aneurysm walls compared to normal vessel walls, but unfortunately, the difference in ∆CNR between the ABAH(+) and ABAH(-) groups was not as significant as expected." (PMID 38509468, 2024). "More interestingly, inhibiting MPO by ABAH prevented the progression of aneurysms in our study, as evidenced by MRA-based expansion rate measurement, MMPs activity assays and Histology study." (PMID 38509468, 2024). "In this work, we monitored dynamic aneurysm changes over 4 weeks using MPO-sensitive MRI with the Mn-TyrEDTA probe to track the active state of inflammation." (PMID 38509468, 2024). "Using MPO as the imaging biomarker, we dynamically and non-invasively assessed the inflammatory state of aneurysms through MPO-sensitive MR imaging." (PMID 38509468, 2024). "Our results suggest that inhibition of MPO attenuated inflammation and expansion of experimental aneurysm and MPO-sensitive MRI showed promise as a noninvasive tool for monitoring aneurysm inflammation." (PMID 38509468, 2024). "In cerebral aneurysm patients, the concentrations of circulating MPO are locally increased in CA sacs to enhance the number of MPO-positive cells such as neutrophils in the aneurysm." (PMID 34611229, 2021). "MPO gene deletion in a mouse model of AAA prevents aneurysm formation and higher levels of MPO and H2O2 in circulating neutrophils are observed in AAA patients." (PMID 33081376, 2020). "It has been observed that plasma levels of NGAL and MPO are increased in the blood of patients with aneurysms." (PMID 29342213, 2018). "Therefore, it was proposed that the presence of MPO might indicate a more delicate wall of aneurysm that is prone to IA rupture." (PMID 34611229, 2021). "This study evaluated myeloperoxidase (MPO) as an imaging biomarker and therapeutic target for aneurysm inflammation using an elastase-induced rabbit model treated with or without 4-aminobenzoic acid hydrazide (ABAH), an irreversible inhibitor of MPO." (PMID 38509468, 2024).
aneurysm (continued). "Simple and multiple logistic regression was used to model the probability of SAH among aneurysm patients and the probability of CVS and infarction among SAH patients, depending on cH3, MPO, and ELA." (PMID 39654759, 2024). "Interestingly, all three components of NETs, MPO, ELA, and cH3, were significantly lower in aneurysm patients than the healthy controls and patients with ruptured aneurysm." (PMID 39654759, 2024). "In aneurysms exhibiting AWE but no myeloperoxidase activity, presence of vasavasorum was described." (PMID 34743248, 2022). "However, currently it is not clear whether MPO especially contributes to aneurysm rupture in the abdominal aorta." (PMID 34572424, 2021).